IL6 (interleukin 6)
Diseases named in the same sentence as IL6 in open-access papers (continued):
Sharing a sentence is not in itself a finding about the gene and the disease.
myocardial infarction (continued). "In this direction, it has been previously reported that aspirated serum in culprit coronary arteries of patients with acute myocardial infarction had significantly higher concentrations of IL-6 compared to peripheral blood early in the course of the event." (PMID 36555579, 2022). "IL-6 is associated with an increased risk of future myocardial infarction (MI) in healthy middle-aged men and could be clinically used as a predictor for the development of ischemic heart disease and other cardiovascular endpoints (PRIME study)." (PMID 34440006, 2021). "In order to validate these findings, we further used TNFα, IL6, and triglycerides to train a neural network for predicting heart attack." (PMID 33510184, 2021). "The monoclonal anti-IL-6 antibody tocilizumab—currently approved for the treatment of RA and cytokine release syndrome—was tested in patients with myocardial infarction in a phase 2 trials." (PMID 33770265, 2021). "For example, elevated serum IL-6 and IL-6 receptor concentrations have been found in PTSD following accidental man-made traumatic events, and enhanced IL-6 response to the mental stress following myocardial infarction." (PMID 34445252, 2021). "GXSTC can reduce the levels of interleukin-1β (IL-1β), interleukin-6 (IL-6) and other inflammatory factors in the serum of rats after myocardial infarction and can also prevent apoptosis of myocardial cells." (PMID 33867992, 2021). "We validated these findings by training a neural network of four factors TNFα, IL6, and triglycerides to predict heart attack." (PMID 33510184, 2021). "Following myocardial infarction, the increased IL-6 synthesis and signaling by myocytes lead to the preservation of heart tissue, in which damage is limited by reducing cell contractility and inducing an anti-apoptotic program." (PMID 33507957, 2021). "The odds of having a heart attack were eight times higher in the presence of elevated triglycerides and pro-inflammatory markers (TNFα and IL6) as compared to presence of pro-inflammatory markers only." (PMID 33510184, 2021). "NF-κB is implicated in the expression of many downstream proinflammatory genes, such as Cox-2, TNF-α, IL-1β, and IL-6, which are involved in the inflammation response in myocardial infarction and myocardial ischemia/reperfusion." (PMID 34304702, 2021). "Animal studies have shown that administration of anti IL6 antibody prior to myocardial infarction reduces the leukocyte and macrophages infiltration and leads to reduced cardiac dilation and improved cardiac function." (PMID 33078375, 2021). "The cytokine response to infection is similar in the acute phase to myocardial infarction, and is triggered by DAMPS and danger signals following pathogenic invasion (stimulating IL-6, TNFα and IL-1β)." (PMID 33629195, 2021). "In the CANTOS trial, subjects with previous myocardial infarction and higher baseline levels of IL-6 presented higher rates of cardiovascular events." (PMID 33495783, 2021). "The pro-inflammatory cytokines released in response to myocardial infarction include IL-1α, IL-1β, IL-6, TNFα, IL-8, IL-18 and small chemokine molecules such as monocyte chemoattractant protein 1 (MCP-1)." (PMID 33629195, 2021). "Elevated levels of inflammatory biomarkers such as C-reactive protein (CRP), interleukin-6 (IL-6), or tumor necrosis factor (TNF) have been shown to be associated with an increased risk of myocardial infarction and mortality." (PMID 33481059, 2021). "The application of HMGB-1 after myocardial infarction also decreased levels of IL-1, IL-6, IL-10 and vascular endothelial growth factor (VEGF)." (PMID 32403440, 2020). "An elevated level of IL‐6 was also observed in patients after myocardial infarction, with IL‐6 level corresponding with the severity of heart failure." (PMID 33124775, 2020).
myocardial infarction (continued). "In the Norwegian tocilizumab non–ST‐segment–elevation myocardial infarction trial, the first randomized trial of interleukin 6 blockade in myocardial infarction, concentration of both C‐reactive protein and troponin T were reduced in the active treatment arm." (PMID 32515246, 2020). "Gabriel AS, Martinsson A, Wretlind B, Ahnve S. IL-6 levels in acute and post myocardial infarction: their relation to CRP levels, infarction size, left ventricular systolic function, and heart failure." (PMID 32876202, 2020). "Huang M, Yang D, Xiang M, Wang J. Role of interleukin-6 in regulation of immune responses to remodeling after myocardial infarction." (PMID 32876202, 2020). "MiR-375 regulates the expression of pro-inflammatory cytokines such as IL1-β, TNFα, and IL-6: therefore, miR-375 decrease also reduces cytokine expression, as shown in a myocardial infarction model." (PMID 32547539, 2020). "The down‐regulation of TNF‐α, IL‐1β and IL‐6 has been found to exert an anti‐inflammatory effect on the development of myocardial infarction." (PMID 32783282, 2020). "Myocardial infarction and reperfusion injury have been associated with the activation of pro-inflammatory cytokines such as TNF-α, IL-1β, and IL-6, and this activation promotes leukocyte activation and extravasation into the LV infarcted area." (PMID 33313409, 2020). "The transplantation of skeletal muscle pericytes in a model of acute myocardial infarction improved cardiac function by reducing hypoxia and increasing angiogenesis due to increased expression of molecules such as IL-6 and LIF." (PMID 32923442, 2020). "Members of the IL-6 cascade measured at 24 h after myocardial infarction are indicative for larger infarct size and decreased cardiac function measured at 4 months." (PMID 30367209, 2019). "TNF-α and IL-6 were increased by 125% and 79% respectively, after myocardial infarction in the normotensive group (WKY + MI) vs. WKY + sham group (p < 0.01)." (PMID 31052164, 2019). "TNF-α and IL-6 are proinflammatory cytokines involved in the synthesis of collagen and scar formation after acute myocardial infarction." (PMID 31205590, 2019). "In the current study, we found that 10 weeks after myocardial infarction in rats, levels of serum IL-6 and TNF-α were significantly increased." (PMID 30789913, 2019). "Previously, negative associations of lysoPC a C17:0 levels with high-sensitivity C-reactive protein (hsCRP), interleukin-6, insulin, and myocardial infarction have been found." (PMID 31406173, 2019). "Other reports evidenced significantly higher levels of CRP and IL-6 in the patients with unstable angina and myocardial infarction, supporting the connection between acute coronary syndromes and inflammatory status." (PMID 31590380, 2019). "IL-6, a pro-inflammatory cytokine that was demonstrated to be increased at the culprit site in myocardial infarction and is also produced by fibrocytes, was also increased upon stimulation with NETs." (PMID 31312919, 2019). "In our study, some of the maximally dysregulated mRNAs, including Il6 and Ptx3 were directly related with myocardial infarction." (PMID 31827539, 2019). "Il6 is one of the inflammatory cytokines that participate in the inflammation response of myocardial infarction." (PMID 31827539, 2019). "A higher frequency of intermediate monocytes is correlated with lower LVEF in patients with congestive heart failure, elevation of ST segment after myocardial infarction and IL-6 production." (PMID 31379862, 2019). "Our study supports further research into targeting the IL-6 cascade in the treatment of acute myocardial infarction." (PMID 30367209, 2019). "Elevated Il6 levels are important risk markers and prognostic factors for myocardial infarction; Il6 also contributes to the remodeling of the left ventricle after myocardial infarction." (PMID 31827539, 2019).
myocardial infarction (continued). "Morroniside is a major component of C. officinalis, a component of ALWPs, and reduces proinflammatory cytokine IL-6 and IL-1β levels in a rat model of acute myocardial infarction." (PMID 30319390, 2018). "Tumor Necrosis Factor (TNF), Interleukin-1β (IL-1β) and Interleukin-6 (IL-6) are markedly increased during myocardial infarction." (PMID 29166391, 2017). "IL-6 has been reported to be increased during myocardial infarction, but its correlation with IS remains controversial." (PMID 29166391, 2017). "Myocardial infarction in the I group significantly increased the concentrations of all the inflammatory cytokines analyzed, including IL-1β, IL-6 and TNF-α, as well as anti-inflammatory cytokine IL-10." (PMID 29057895, 2017). "Myocardial infarct sizes, histological scores, levels of circulating and myocardial IL-6 and TNF-α, the expression of HMGB1, TLR4, MyD88 and NF-κB, and the degradation of IκB were significantly increased in the I/R group compared with the sham group (P<0.01)." (PMID 28222157, 2017). "One study indicated that the upregulation of myocardial pro-inflammatory genes (TNF-alpha, IL-1beta and IL-6) and coronary thrombosis in rats with myocardial infarct induced by isoproterenol were both stopped by zingerone pre-treatment." (PMID 29206854, 2017). "Since each subject suffers from different symptoms, different biomarkers were examined, e.g., IL-6 was checked for coronary artery disease, cTnI was checked for myocardial infarction, and NT-proBNP was checked for congestive heart failure." (PMID 29186872, 2017). "Levels of plasminogen activator inhibitor, interleukin 6, and C-reactive protein in patients with myocardial infarction on day 1 and 12 of hospitalization." (PMID 27725801, 2016). "Macrophage is a major cellular component of inflammatory reaction in myocardial infarction, generating pro-inflammatory cytokines such as IL-1, IL-6 and TNF-α that play central roles in the initiation and maintenance of inflammation." (PMID 26882996, 2016). "The IL-6 hypomethylation-related riskestimates tended to be stronger for acute myocardial infarction(ptrend = 0.006)." (PMID 27627640, 2016). "It is well accepted that circulating biomarkers, including C-reactive protein and interleukin-6, reliably predict major cardiovascular events, including myocardial infarction or death." (PMID 25960621, 2015). "When patients with atherosclerotic burden underwent short-term statin treatment, IL-6 levels were decreased, and myocardial infarction and death were reduced." (PMID 26092124, 2015). "Findings from a 6-year study showed that among healthy men at baseline, IL-6 levels were higher (1.81 pg/mL) in those who experienced a subsequent myocardial infarction." (PMID 26378783, 2015). "Pro-inflammatory IL-6 has been reported to be involved in the remodeling of left ventricle after myocardial infarction and induced heart failure leading to skeletal muscle atrophy and heart disorders." (PMID 25888309, 2015). "In line with current data, up-regulation of IL-6 in CHF myocardium and cardiac fibroblasts suggest a link between IL-6 and cardiac fibrosis in heart failure secondary to myocardial infarction." (PMID 25997003, 2015). "In the setting of myocardial infarction studies indicate that short-term IL6 signaling can protect myocardial tissue in response to acute damage, whereas over the long term increased levels of IL6 play a causative role in CVD." (PMID 26544186, 2015). "Interleukin-6 (IL-6) is an inflammatory cytokine whose levels increase significantly during myocardial infarction (MI)." (PMID 25516764, 2014). "On the one hand, high IL-6 was proposed to predict 30-day mortality in patients with cardiogenic shock after myocardial infarction." (PMID 25516764, 2014). "Patients with an acute myocardial infarction had the highest measures of IL-6 and ICAM-1 as has been reported in previous studies." (PMID 23349778, 2013).
myocardial infarction (continued). "It has been suggested to act with IL-6 as the main acute phase response mediator in patients with myocardial infarction." (PMID 24194869, 2013). "The highest values for IL-6 were obtained in patients who had a myocardial infarction and were dUTPase positive." (PMID 23349778, 2013). "Elevated levels of IL-1 have been described in acute myocardial infarction as soon as 2 hours after symptoms onset and 6 to 9 hours before an increase in IL-6." (PMID 23028694, 2012). "Elevated plasma levels of IL6 and TNFα were detected in patients with stable or unstable angina and myocardial infarction." (PMID 22883023, 2012). "We repeatedly determined plasma IL-6 in 955 myocardial infarction survivors from six European cities (n = 5,539)." (PMID 19750100, 2009). "People with the highest IL-6 levels were two to five times more likely to have a heart attack, stroke or other cardiovascular episode than those with the lowest levels." (PMID 17374166, 2007). "Furthermore, two other studies indicate that IL-6 expression has been evidenced in unstable angina and myocardial infarction." (PMID 41550503, 2026). "In the ASSAIL-MI (ASSessing the effect of Anti-IL-6 treatment in Myocardial Infarction) trial we showed that mitigation of inflammation by blocking the interleukin-6 (IL-6) receptor with the monoclonal antibody tocilizumab leads to improved outcomes in patients with MI." (PMID 40547027, 2025). "Beyond early events, select studies linked persistently elevated IL-6 to increased major adverse cardiovascular events (MACE), myocardial infarction, restenosis, and mortality over longer-term follow-up, suggesting that it persists as a risk factor beyond successful revascularization." (PMID 41440557, 2025). "Specifically, in the Anti-IL-6 treatment in Myocardial Infarction (ASSAIL-MI) trial, a single infusion of tocilizumab was shown to increase myocardial salvage (as measured by magnetic resonance imaging) in patients with ST-segment elevation myocardial infarction compared to placebo." (PMID 40884675, 2025). "However, direct evidence of PTX-3 and IL-6 modulation by butylphthalide in myocardial infarction models remains limited, warranting further investigation." (PMID 41281269, 2025). "It induces cells to produce and release a multitude of inflammatory factors, such as IL-6, IL-1β, and TNF-α, which mediate the cascade of inflammatory responses, causing the necrosis of cardiomyocytes, an increase in myocardial infarction area, and a decrease in cardiac function." (PMID 40809170, 2025). "The observations suggest that IL-1β, IL-6, and IL-8 play an important role in myocardial infarction pathogenesis and other inflammatory diseases and may contribute to inflammation-resolved damage." (PMID 38543157, 2024). "The results showed that resveratrol could reduce ST segment, cTn-I, cTn-T, CK, CK-MB, LDH, LVEDP, ROS, MDA, TNF-α, IL-6, AI levels and myocardial infarction size." (PMID 38313308, 2024). "On the same note, troponin expressing myocardial necrosis extent was positively correlated with white blood cells, neutrophils, NLR, S100A8/A9, NETS, and IL-6, strengthening the conclusion that the activated neutrophils contribute to myocyte dysfunction after myocardial infarction." (PMID 38791147, 2024). "Our study strongly suggests that IL-6 could be a powerful marker in evaluating the Myocardial Infarction." (PMID 38854770, 2024). "Similarly, male EH-WS mice also have increased expression of IL-6 and Vcam-1 in the aorta, which have been shown to be predictive of peripheral atherosclerosis progression and acute myocardial infarctions." (PMID 38659910, 2024). "Administration of taurine (100 mM) in Wistar rats 30 days after coronary artery occlusion-induced ischemia significantly decreased myocardial infarct size and reduced expression of IL-6 and TNF-α, suggesting that taurine provides anti-inflammatory cardio-protective effects." (PMID 37299525, 2023).
myocardial infarction (continued). "Interleukin 6 was also a strong predictor of mortality after acute myocardial infarction." (PMID 35837017, 2022). "Based on the inflammatory and fibrotic markers commonly observed in response to myocardial infarction and development of heart failure, we assessed the expression of mRNA for Tnfa, Il1b,Il6, Il18, Ccl2, Ccl3, Cxcl1, Cxcl2, Col1a1, Col3a1, Postn, and Tlr4 at 1 and 3 months." (PMID 35411847, 2022). "For example, the elevation of interleukin-6 (IL-6) was found in induced myocardial infarction." (PMID 36291959, 2022). "In coronary artery disease this medicament decreases IL-6 level, increases TGF-β and IL-22, while in acute myocardial infarction it decreases IL-6, TNF-alfa, and C reactive protein (CRP), which in both cases should lead to alleviation of inflammation-related complications." (PMID 35163696, 2022). "Chronic kidney disease activates vascular inflammatory processes and as consequence high levels of inflammatory biomarkers such as interleukin-6 (IL-6), C-reactive protein (CRP), and tumor necrosis factor (TNF) are associated with an increased risk of myocardial infarction and mortality." (PMID 35453821, 2022). "In acute myocardial infarction, valsartan decreases IL-6, TNF-alfa and CRP." (PMID 35163696, 2022). "The mtDNA induced by myocardial infarction could inhibit the secretion of IL-6 and TNF-α in granulocytes, which may account for the patients’ susceptibility to infection after injury or myocardial infarction." (PMID 35454769, 2022). "In clinical studies, IL-6 consistently associates with an increased risk of future non-fatal myocardial infarction and coronary artery disease, even larger than cemented cardiovascular risk factors, such as blood pressure and LDL." (PMID 36555579, 2022). "Indeed, in individuals with acute myocardial infarction, the rise in IL-6 is tightly related to a drop in T3, due to the inhibitory activity that IL-6 exerts on D2." (PMID 36676947, 2022). "However, the area of myocardial infarction and the level of troponin I were both significantly lower in the IL-6-treated mice than in the control mice." (PMID 33428604, 2021). "Circulating CD14+HLA-DRneg/low monocytes secrete high levels of TNFα, IL-6, and IL-1β which promote proinflammatory immune responses; in the expansion of this monocyte population after myocardial infarction correlates with both cardiac damage and physiological function." (PMID 34589791, 2021). "The ability of elevated CRP, CA 19-9 and IL-6 to predict one-year mortality, in terms of ROC statistics, was comparable to the ability of low-density lipoprotein cholesterol and apolipoprotein B to predict myocardial infarction." (PMID 34572824, 2021). "It is pointed out that interleukins such as IL-1, IL-4, IL-6, and IL-8 are involved in the development of myocardial infarction, most of which are released into the circulation and serve as inflammatory biomarkers, and these effects were also reflected in our results." (PMID 34957234, 2021). "Elevated IL-6 serum levels in patients with coronary heart disease (especially in those with acute myocardial infarction) may be predictive of poor outcomes." (PMID 33428604, 2021). "It was reported that IL-6 has an unfavorable effect on the function of EPC after myocardial infarction, but it is unknown whether IL-17 can regulate the circulating EPCs." (PMID 33869300, 2021). "IL-6 is a pleiotropic cytokine, and in the acute phase of ischemia–reperfusion injury and myocardial infarction in a rat model, it acts as a protective cytokine to host injury while chronically becomes pathogenic to the host, leading to chronic inflammation and cardiac fibrosis." (PMID 34179145, 2021). "The I/R process is thought to trigger a pronounced inflammatory response, and IL-6 may produce two completely different effects in acute myocardial infarction and I/R injury models." (PMID 33428604, 2021).